STAT3 (signal transducer and activator of transcription 3)
Diseases named in the same sentence as STAT3 in open-access papers (continued):
Sharing a sentence is not in itself a finding about the gene and the disease.
breast cancer (continued). "The IL-6/JAK2/STAT3 pathway was found to be active in CD44+/CD24− breast cancer cells, and inhibitors blocking this pathway suppressed growth of xenograft tumors." (PMID 24743778, 2014). "Constitutive activation of STAT3 in breast cancer cell lines and primary cancers has been demonstrated by many groups." (PMID 25268165, 2014). "In vivo, STAT3 signaling was critical for breast cancer cell tumorigenicity and for the formation of local relapse after surgery." (PMID 25026286, 2014). "The present study demonstrated that STAT3 is significantly activated in the B cells of patients with breast cancer." (PMID 25013518, 2014). "In breast cancer cells, STAT3 leads to increased expression of BCL6 and STAT5 mediates repression of this gene." (PMID 24762632, 2014). "In breast cancer cells, the pharmacological inhibition of STAT3 activation using a small molecule inhibitor, Stattic, potentiated HNK-mediated inhibition of vimentin." (PMID 25405202, 2014). "This would suggest that β-catenin is transcriptionally regulated by STAT3 and is consistent with studies in breast cancer showing direct binding of STAT3 to the β-catenin promoter." (PMID 25348333, 2014). "The importance of targeting more than one pathway, or more than one STAT protein, is underscored by the finding that STAT3 suppresses the transcription of proapoptotic genes in breast cancer cells." (PMID 24913037, 2014). "More importantly, HER2/ER/STAT3 activation signaling held true in human breast cancer patient tissues." (PMID 24297508, 2014). "It is interesting that STAT5 is also reported to be associated with favourable outcome in breast cancer for both total STAT5 and nuclear phospho-STAT5 yet, like STAT3, this is considered to have a pro-oncogenic role in early disease development." (PMID 24728078, 2014). "In the present study, our results showed that niclosamide, a new potent inhibitor of Stat3 signaling pathway, decreased expression of Stat3 phosphorylation at tyrsione residue 705 in 4T1 mouse mammary cancer cells." (PMID 24416452, 2014). "Increased STAT3 signaling has also been observed in breast cancer ALDH+ stem cell populations and targeted inhibition of STAT3 reduces the tumorogenic capacity of this stem population." (PMID 24722453, 2014). "Although STAT3 is activated inappropriately in a majority of breast cancers, an understanding of the physiological roles of STAT transcription factor in mammary epithelium actually began with STAT5." (PMID 24762632, 2014). "A number of investigators had found that a majority of primary breast cancers display STAT3 activation." (PMID 24762632, 2014). "HMGB1–TLR2 signaling via signal transducer and activator of transcription factor 3 (STAT3) and Smad3 activation enhances breast cancer stem cell self-renewal and increases breast cancer metastasis." (PMID 24723911, 2014). "It was shown that STAT3-RANTES autocrine signaling is essential for tamoxifen resistance in breast cancer." (PMID 24297508, 2014). "This transactivation increases STAT3 transcriptional activity and thus promotes breast cancer carcinogenesis." (PMID 24743778, 2014). "In fact, a miR46b-mediated negative feedback loop present in normal breast cell lines, which is activated by Stat3, is lost in breast cancer cell lines with sustained Stat3 activity." (PMID 25268166, 2014). "We elucidated CXCR7-mediated signaling pathways and showed that CXCL12 induced p44/p42 ERK and p-STAT3 in breast cancer cells." (PMID 24886617, 2014). "Aberrant activation of STAT3 is commonly found in a large variety of tumors, including breast cancer." (PMID 25026286, 2014). "STAT3 is activated commonly (that is, in more than half of all patients) in a wide spectrum of human cancers, including cancers of the breast, prostate, ovary, and pancreas." (PMID 24762632, 2014). "Inhibitors of STAT3 also suppress cell proliferation and promote apoptosis in breast cancer, colorectal cancer, gastric cancer and lung cancer." (PMID 24743778, 2014).
breast cancer (continued). "In vitro application of these inhibitors has shown to inhibit STAT3 activation, cell invasion, and colony formation in breast cancer cell lines." (PMID 25202681, 2014). "For example, STAT3 has been considered a fundamental component of resistant tumor growth in breast cancer, head and neck squamous cell carcinoma and lung cancer due to induction of an invasive EMT-like phenotype." (PMID 24297508, 2014). "While 40% of all breast cancers display activation of STAT3 alone, only 7% of tumors show isolated STAT5 activation." (PMID 24762632, 2014). "Because STAT3 influence cancer cell ability for invasion and migration and microarray analysis in canine mammary tumor cells showed downregulation of Keratin 17 due to MDSC co-culture, we examined a role of IL-28 in EMT." (PMID 25075523, 2014). "STA-21 is a natural deoxytetrangomycin, an angucycline antibiotic, that specifically binds to SH2 domain and abrogates STAT3 dimerization and nuclear translocation, thereby significantly inhibits breast cancer cell growth and survival." (PMID 24743778, 2014). "Rather, progesterone can rapidly activate the Src/Ras/MAPK, PI3 kinase/Akt, and JAK2/Stat3 signaling pathway in breast cancer." (PMID 23484104, 2013). "Hyaluronan stimulates the interaction between CD44 and Nanog, an embryonic stem cell transcription factor, leading to activation of STAT3, and knockdown of STAT3 by siRNA blocks hyaluronan-induced breast cancer cell growth." (PMID 23326564, 2013). "SC-1 and SC-43 showed greater inhibition of p-STAT3 than sorafenib at the same indicated doses in the tested breast cancer cells." (PMID 23938089, 2013). "STAT3 is constitutively activated in human solid tumour cancers such as breast cancer and prostate cancer, as well as myelomas and NK cell lymphomas." (PMID 23372833, 2013). "The increase in expression of phosphorylated STAT3 in the ALDH+ subpopulation suggests a possible role for this pathway in breast cancer stem-like cells." (PMID 24376586, 2013). "Ectopic expression of STAT3 reversed downregulation of p-STAT3 and reduced the apoptosis caused by sorafenib, SC-1 and SC-43 in MDA-MB-468 cells, suggesting that STAT3 mediates the apoptotic effects of these agents in breast cancer cells." (PMID 23938089, 2013). "STAT3 activation is frequently detected in breast cancer and this pathway has emerged as an attractive molecular target for cancer treatment." (PMID 24376586, 2013). "Recently, a new study found that miR-155 targeting suppressor of cytokine signaling 1 (SOCS1) who inhibit STAT3 functions as an oncomicroRNA in a breast cancer cell line." (PMID 23437123, 2013). "Novel sorafenib analogues SC-1 and SC-43 induce apoptosis through SHP-1 dependent STAT3 inactivation and demonstrate greater potency than sorafenib in human breast cancer cells." (PMID 23938089, 2013). "Our study also highlights the feasibility of targeting SHP-1 dependent p-STAT3 inhibition in breast cancer therapy." (PMID 23938089, 2013). "Human prostatic carcinoma DU145 and breast cancer MDA-MB-468 cell lines showed constitutive STAT3 activity." (PMID 23704931, 2013). "Taken together, these results support that breast cancer stem-like cells are sensitive to STAT3 inhibitors." (PMID 24376586, 2013). "STAT3 shRNA significantly suppressed ALDH+ breast cancer stem-like cell tumor growth compared with lentivirus GFP as a control." (PMID 24376586, 2013). "Taken together, these results confirm that sorafenib analogues SC-1 and SC-43 increased SHP-1 activity which downregulated p-STAT3 and led to tumor inhibition in a breast cancer xenograft model." (PMID 23938089, 2013). "The inhibition of STAT3 by LLL12 also down-regulated the expression of several known STAT3-regulated genes in breast cancer stem-like cells such as Cyclin D1, survivin, Bcl-2, Bcl-XL and an IL-6 regulated gene, Notch1." (PMID 24376586, 2013).
breast cancer (continued). "This is consistent with recent results demonstrating that the cytokine IL-6 is able to stimulate breast cancer stem cells and JAK2/STAT3 signaling pathway is required for growth of breast cancer stem cells." (PMID 24376586, 2013). "Our data also demonstrate an important role of constitutive STAT3 signaling in breast cancer stem-like cell growth in vitro and in mouse tumor models in vivo." (PMID 24376586, 2013). "In a variety of human malignancies, including breast cancer, constitutive activation of STAT3 is correlated with the tumor progression and a poor prognosis." (PMID 24386318, 2013). "The constitutive activation of STAT3 and NF-kB and up-regulation of hTERT signaling pathway identifies novel therapeutic targets for breast cancer." (PMID 24386318, 2013). "The expression level of MMP-9 has been correlated with the level of activated STAT3 in human breast cancer." (PMID 23326564, 2013). "In breast cancer, receptor gp130 mediates IL-6 signals; inhibiting IL-6 signaling and production in turn inhibits in vitro activation of STAT3 as well as in vivo tumor cell proliferation and number of metastases." (PMID 23710200, 2013). "Metformin has been shown to target Stat3 and induce apoptosis in triple-negative breast cancers as well as significantly decrease serum IL-6 level in breast cancer patients." (PMID 23372803, 2013). "Recent microarray studies have shown high expression levels of Stat1 and Stat3 in primary breast cancers, with several studies grouping Stat1 within the top one percent of most highly expressed genes." (PMID 23520493, 2013). "They found that the IL-6/JAK2/Stat3 pathway was preferentially active in CD44+ CD24− breast cancer cells compared to other tumor cell types." (PMID 23401782, 2013). "And the research also showed overexpression of miR-155 in breast cancer cells leads to constitutive activation of signal transducer and activator of transcription 3 (STAT3) by inhibiting SOCS1 expression." (PMID 23437123, 2013). "NANOG has also been identified in breast cancer cells and was found to mediate multidrug resistance via activation of STAT3 signaling suggesting that NANOG is a potential target for breast cancer therapeutics." (PMID 23662114, 2013). "Further studies as well as more samples are warranted to clarify the relationship between SHP-1 and p-STAT3 expression in various subtypes of breast cancer." (PMID 23938089, 2013). "STAT3 has also been linked to EMT, is constitutively activated in many human malignancies, has a well-defined link to breast cancer progression and is required for survival of cultured tumour cells." (PMID 23919497, 2013). "To define molecular function of STAT3 in breast cancer, we chose two breast cancer cell lines which contain the constitutively activated STAT3 (pSTAT3), MDA-MD-231 and MCF7-HER2." (PMID 24386318, 2013). "To further validate the role of STAT3 in SC-1- and SC-43-induced apoptosis in breast cancer cells, we next generated MDA-MB-468 cells with stable expression of STAT3." (PMID 23938089, 2013). "In particular, STA-21 and S3I-201 selectively target the DNA-binding domain of STAT3 and effectively suppress its activity in rhabdomyosarcoma, osteosarcoma, and breast cancer." (PMID 23382914, 2013). "We also showed that MEK1/2 and STAT3 stimulation in response to FGF1 stimulation is increased in HEK293 cells expressing the FGFR2-IIIb breast cancer mutants." (PMID 23527311, 2013). "We, therefore, examined the effects of STAT3 inhibition on this more highly enriched population of breast cancer stem-like cells." (PMID 24376586, 2013). "MDSC-derived IL-6 and sIL-6Rα induced persistent activation of STAT3 and increased invasiveness of breast cancer cells via an IL-6 trans-signaling mechanism." (PMID 24021059, 2013). "Stat1 and Stat3 are expressed in both the tumor cell and stromal cell compartments of breast cancers." (PMID 23520493, 2013).
breast cancer (continued). "Marotta and coworkers targeted the JAK2/Stat3 signaling pathway for specific breast cancer therapies by highlighting the difference between distinct breast cancer cell types." (PMID 23401782, 2013). "In summary, our results suggest that novel sorafenib analogues SC-1 and SC-43 induce apoptosis through SHP-1 dependent STAT3 inactivation and demonstrate more potent apoptotic activities than sorafenib in human breast cancer cells." (PMID 23938089, 2013). "Constitutive activation of AKT and STAT3 has also been reported with high frequency in human breast tumors as well as in DMBA induced mammary tumors." (PMID 23555785, 2013). "Chip assay revealed that STAT3 binds to consequence sequences of STAT3 binding sites within hTERT promoter in aggressive breast cancer cell lines." (PMID 24386318, 2013). "Human breast cancer samples have been known to contain high levels of p-Stats, in particular p-Stat1, p-Stat3, and p-Stat5." (PMID 23520493, 2013). "These in vivo results were consistent with the in vitro cancer stem cell data using LLL12, indicating that LLL12 is a potent STAT3 inhibitor in the suppression of tumor growth of breast cancer stem-like cells in the mouse model in vivo." (PMID 24376586, 2013). "The present study identifies STAT3 as an important signaling molecule interacting with CD44 and demonstrates the essential role of CD44-STAT3 signaling in breast cancer invasion." (PMID 23326564, 2013). "The inhibition of LLL12 on these STAT3 target genes in ALDH+ stem cell-like breast cancer cells was quantified and normalized to GAPDH." (PMID 24376586, 2013). "Studies with human breast cancer cells demonstrated that the constitutive activation of STAT3 is a crucial contributor to the growth, survival and invasion of cancer cells." (PMID 23326564, 2013). "Treatment of these mice with LLL12 resulted in significant suppresses (P<0.05) of tumor volume and tumor mass, and STAT3 phosphorylation in SUM159 breast cancer stem-like cells." (PMID 24376586, 2013). "Signal transducers and activators of transcription 3 (STAT3) signaling is constitutively activated in various cancers including breast cancer and has emerged as a novel potential anti-cancer target." (PMID 23938089, 2013). "Similar inhibition of STAT3 phosphorylation, and breast cancer stem cell viability were observed using STAT3 ShRNA." (PMID 24376586, 2013). "The inhibition of STAT3 by LLL12 also down-regulated the expression of known STAT3 target genes in ALDH+ breast cancer cells related to cancer cell proliferation, survival, and angiogenesis, including Cyclin D1, survivin, Bcl-2, Bcl-XL, MMP-2, and MMP-9." (PMID 24376586, 2013). "On the other hand, inhibition of STAT3 signaling with STAT3 small hairpin RNA (shRNA) or use of STAT3 phosphorylation inhibitors repressed the formation and growth of xenograft tumors in mice as well as the invasive potential of breast cancer cells." (PMID 23326564, 2013). "Our data suggest that STAT3 activation is responsible for the hTERT up-regulation in the aggressive breast cancer cell lines." (PMID 24386318, 2013). "Our data on STAT3 activation are consistent with previous studies on the preferential activation of STAT3 in CD44 positive breast cancer stem cells." (PMID 24386318, 2013). "JSI-124, previously identified as cucurbitacin I, reduced the levels of phosphotyrosine of constitutively activated STAT3 in many human cancer cell lines including lung and breast carcinomas." (PMID 24199193, 2013). "Progestins downregulate miR-16 in breast cancer cells via the classical PR and a hierarchical interplay between Stat3 and c-Myc." (PMID 22583478, 2012).
breast cancer (continued). "All the results are consistent and intercomparable in demonstrating the role of PTPMeg2 in regulation of STAT3 activity in the breast cancer." (PMID 22394684, 2012). "In regards to tumorigenesis, despite having a pro-apoptotic function in mammary gland involution, Stat3 has been found to be constitutively active in breast cancers at low levels and these cancers appear to become addicted to Stat3." (PMID 22574198, 2012). "Especially, STAT3 is constitutively activated in many human cancers, including prostate cancer, breast cancer, squamous cell carcinoma of the head and neck (SCCHN), nasopharyngeal carcinoma and multiple myelomas." (PMID 22260501, 2012). "Our data highlights the potential use of Rac and STAT3 inhibition in treatment of invasive human breast cancer and the benefit of studying novel cancer treatments using three-dimensional primary tumour tissue explant cultures." (PMID 22689141, 2012). "In breast cancer, IL-6 is known to activate STAT3, which has been shown to be an important signaling molecule that is associated with an unfavorable prognosis; in fact, the principal mechanism of STAT3 activation is via the IL-6/gp130/Jak pathway." (PMID 22235336, 2012). "It is concluded that STAT3 plays an essential role in breast cancer stem cells, which correlated with tamoxifen resistance." (PMID 23554768, 2012). "Constitutive activation of STAT3 is frequently observed in many human tumors, including melanoma, breast cancer, head and neck cancer, glioma and prostate cancer." (PMID 22911830, 2012). "Signal transducer and activator of transcription 3 (STAT3) is over-activated or phosphorylated in breast cancers." (PMID 22394684, 2012). "Hyper-phosphorylation of STAT3 has been observed in a variety of hematopoietic malignancies and solid tumors, including breast cancer." (PMID 22394684, 2012). "In breast cancer cells, the activated oncogene STAT3 binds to the promoter regions of MEK5 and induces transcription, conferring a critical survival signal." (PMID 22458985, 2012). "Our own findings demonstrated that progestins induce the transcriptional activation of signal transducer and activator of transcription 3 (Stat3), which is an absolute requirement for progestin-mediated breast cancer growth." (PMID 22583478, 2012). "Down regulated expression of PTPMeg2 is correlated with elevated phosphorylated STAT3 in human breast cancer tissues." (PMID 22394684, 2012). "Combination of doxorubicin with PEITC effectively suppressed HER2 and STAT3 phosphorylation in breast cancer cells, resulting in enhanced apoptosis as compared to individual treatments respectively." (PMID 22824293, 2012). "The aim of this study was to determine the role of PTPMeg2 as a phosphatase in regulation of the activity of STAT3 in breast cancers." (PMID 22394684, 2012). "apart from its general anti-proliferative effects, strategies targeting the STAT3 signaling pathway can directly inhibit breast cancer stem cells and control tumorigenesis at its source." (PMID 23554768, 2012). "In this study, we establish three new findings that elucidate the role of Anxa2 in the proliferation and invasion of breast cancer SK-BR-3 cells, and the effect of Anxa2 on the stimulation of Stat3 pathways." (PMID 23691485, 2012). "Constitutive Stat3 activity has been observed in ER-negative invasive breast cancer samples and metastatic cell lines." (PMID 22879872, 2012). "Our findings indicate that progestins, acting through the classical PR and via Stat3 and c-Myc, downregulate miR-16, which is a potent tumor suppressor in breast cancer." (PMID 22583478, 2012). "An in vivo interaction of endogenous PTPMeg2 and STAT3 proteins was observed in the mouse brain tissue and breast cancer MCF7 cells." (PMID 22394684, 2012). "HSE effectively down-regulated the expression of Brk in breast cancer cell lines by the activation of STAT3 and STAT5b." (PMID 22792362, 2012).